DKK1 (dickkopf Wnt signaling pathway inhibitor 1)
Diseases named in the same sentence as DKK1 in open-access papers (continued):
Sharing a sentence is not in itself a finding about the gene and the disease.
cancer (continued). "Cancer that is resistant to chemotherapy often exhibits reduced expression of Wnt pathway inhibitors, such as WIF1, SFRP, and DKK1." (PMID 40430852, 2025). "CKAP4-targeted aptamers present dual-action blocking of CKAP’s interaction with DKK1 and, thus, disrupting PIK/Akt signaling as well as impeding cancer cell adhesion and migration by decreasing internalization and recycling of α5β1 integrin." (PMID 41149482, 2025). "Knockdown of either DKK1 or CKAP4 results in impaired Akt activity and colon cancer formation in cancer cells resistant to oxaliplatin." (PMID 41149482, 2025). "The interaction between DKK1 and CKAP4 promotes metastasis by enhancing cancer cell migration and evasion." (PMID 41149482, 2025). "Thus, either DKK1 or CKAP4 could serve as molecular targets for anti-cancer therapy." (PMID 39795613, 2025). "Some clinical investigations have reported elevated serum DKK1 levels in ESCC, GC, and PC cancers, indicating its role as a promising biomarker in GI malignancies." (PMID 40943055, 2025). "Combination with p63 or DKK1 or both resulted in a significantly reduced MFS and OS for patients with HPV + CD147 + CD15 + p63 cancers." (PMID 39333233, 2024). "The results associated a notable potential to predict aggressive growing metastasizing cancers with the combinations HPV + p63 + CD15, HPV + DKK1 and HPV + CD147 + CD1511–13." (PMID 39333233, 2024). "PeCa cells release CXCL8, DKK1, and CD147, leading to reprogrammed fibroblasts and TAN promoting cancer progression and metastasis." (PMID 39333233, 2024). "Expression of DKK1, DKK2, and SFRP1 was verified by IHC staining of clinical specimens of colon normal epithelium, adenomatous, and cancer tissues." (PMID 38334454, 2024). "TWIST enhances the metastatic potential of prostate cancer and promotes cancer progression through epithelial–mesenchymal transition (EMT), the expression of dickkopf homolog 1 (DKK-1), and enhancing osteomimicry of prostate cancer cells." (PMID 38791037, 2024). "Dickkopf-1 (DKK-1), a secretory antagonist of the Wingless/integrated-1 (WNT) signaling pathway, has functionality in both bone homeostasis and cancer progression." (PMID 38067123, 2023). "In contrast, DKK1 was downregulated in colorectal cancer (CRC) and participated in the suppression of CRC tumorigenesis and angiogenesis, acting as a cancer suppressor gene." (PMID 37835450, 2023). "We conducted an oncology protein array to measure 84 major cancer-related proteins in both A549 cells and A549 EVs and found that EpCAM, EGFR, Dkk-1, Galectine-3, Endostatin, E-Cadherin, FGF basic, Vimentin, and progranulin are the top nine hits." (PMID 36834913, 2023). "For reference, the most prevalent non-cancer genes were PTPRN2 and DKK1, which were found in five and four cancer types, respectively." (PMID 37558831, 2023). "Cytoskeleton-associated protein 4 (CKAP4) is a novel DKK1 receptor that binds to DKK1 to activate AKT signaling and enhance cancer cell proliferation." (PMID 35712490, 2022). "Here, the authors show that BCSCs secrete DKK1 to protect metastasizing cancer cells from ferroptosis via upregulation of SLC7A11, and further show that the combination of a ferroptosis inducer with a DKK1 inhibitor reduces metastasis." (PMID 35296660, 2022). "In vitro and in vivo studies confirm the positive feedback loop between DKK1 and FOXM1 promotes cancer cell proliferation, and our clinical data also indicates that PDAC and ESCC cases that simultaneously expressed DKK1 and FOXM1 show poor clinical prognosis." (PMID 34117362, 2021). "Other clinical trials using anti-DKK1 mAb, such as BHQ880 and PF-04840082 were also carried out to treat certain cancers." (PMID 34899842, 2021). "Epigenetic modification of DKK1 has been proved to act on Wnt/β-catenin signaling pathway, such as DNA demethylation mediated by TET1 during development and progression of cancer." (PMID 34863303, 2021).
cancer (continued). "Dickkopf-1 (DKK1), as a WNT signaling pathway inhibitor, is involved in the development of several types of cancers." (PMID 34899842, 2021). "With the here-reported regulation of DKK1 expression, ATF5 becomes further involved in the modulation of Wnt/β-catenin-mediated target gene expression, and thus cancer progression and metastasis also for CRC." (PMID 35008201, 2021). "More directly, our findings provided evidence that the expression of DKK1 was correlated with the level of Th1 markers (STAT1 and IFNG) and Th2 markers (GATA3 and STAT6) in various cancers, such as ACC, KICH, MESO, and PAAD." (PMID 34899842, 2021). "DKK1, a secretory glycoprotein of the DKK family, had been found to play vital roles both in cancers and AS." (PMID 34803487, 2021). "The elevated expression of both DKK1 and DKK3 in carcinoma tissues of HCC patients as compared to non-carcinoma tissues have been reported." (PMID 33562077, 2021). "Sclerostin, DKK-1, and FGF23 are osteocyte-specific markers; they were studied to evaluate their contribution to osteocyte/cancer cell crosstalk." (PMID 32640686, 2020). "At the cancer type level, some of the perturbations we identified, such as IGF2BP3 and DKK1-MDFI, have already been suggested to be KIRP biomarkers." (PMID 32152446, 2020). "In particular, we selected target genes known to be critical in cancer development, namely TCF7, DKK1, WISP1, MYCC, and SOX17." (PMID 32283844, 2020). "We were also interested in studying the effect of DKK1 on TGF-β expression since it has been shown that TGF-β is capable of inducing EMT, thereby facilitating cancer dissemination." (PMID 31568519, 2019). "Western blot analysis confirmed that UNC0638 treatment dramatically reduced the level of H3K9Me2, increased the levels of APC2, DKK1, and WIF1 proteins, and resulted in decreased β-catenin in these cancer cells." (PMID 30348169, 2018). "It has been reported that LAST2, DKK1 and TXNIP are targeted by miRNA‐372/373 in different cancer cells." (PMID 30171794, 2018). "As model inhibitors, we used sFRP1 and Dkk1 and as model cells, we used known cell lines that mimic the level of LoF of APC in human cancer cells, both with truncated APC (APC1572T) and with attenuated levels of full-length APC (APCneoR, APCneoF)." (PMID 28708837, 2017). "In cancer cells, IL1β induced nitric oxide production and that this upregulated WNT/β-catenin signaling by inhibiting DKK1 expression." (PMID 29165387, 2017). "Repression of the Wnt pathway by extracellular inhibitors, such as Dickkopf1 (DKK1), Wnt inhibitory factor 1 (WIF1), or secreted frizzled-related proteins (SFRPs), has also been observed in human cancers." (PMID 27713747, 2016). "In renal carcinoma, DKK1 and DKK2 expression is epigenetically suppressed, and their ectopic expression induces apoptosis, and decreases invasion, of cancer cells." (PMID 24091497, 2014). "Since DKK-1 is a secreted protein, serum level of DKK-1 and its prognostic potential have been investigated in several cancers." (PMID 24612589, 2014). "PCa patients and controls were comparable for age and DKK-1 serum levels, whereas PSA was significantly lower in non-cancer patients." (PMID 24655661, 2014). "This study demonstrated that in HCV infected liver tissues hypermethylation at promoter regions of key cancer related genes SFRP2 and DKK1, appears early at CH and LC stages, long before the appearance of HCC." (PMID 24947038, 2014). "A few but growing number of immunogenic antigens have been discovered in MM, including idiotypes on MM immunoglobulin, MUC1, WT1, a subgroup of cancer-testis antigens (CTAs), receptor for hyaluronic acid-mediated motility (RHAMM), Dickkopf1 (DKK1) and HM1.24." (PMID 22611422, 2012). "More studies, especially direct comparison of DKK-1 in different cell types at the same condition, are needed in order to better understand the complex functions of DKK-1 in relation to cancer development." (PMID 20920327, 2010).
cancer (continued). "In cancer cell lines such as MDA231 and HCT116 where β-catenin is upregulated, the addition of inhibitors of the canonical Wnt pathway (other than DKK1) led to a marked reduction of free β-catenin." (PMID 17245340, 2007). "Reversely, DKK1 knockdown appeared to have a negative impact on cancer cells, proliferation, and migration by enhancing apoptosis." (PMID 39795613, 2025). "Moreover, a substantial reduction in DNA methylation results in the downregulated expression of inhibitors of Wnt, including Dickkopf-related protein 1 (DKK1), Wnt inhibitory factor 1 (WIF-1), and various frizzled-related proteins (SFRP1-5), in cancer cells." (PMID 40006021, 2025). "Notably, proteins such as DKK‐1, VEGF, IL‐8, PDGF‐AA, and angiogenin were downregulated within both the PDAC and TNBC cancer cells." (PMID 40116596, 2025). "DKK1 promotes an immunosuppressive TME that benefits MDSC expansion by regulating β-catenin-independent Wnt signaling, resulting in suppression of CD45+ T cell proliferation, and contributing to cancer immune evasion." (PMID 40943055, 2025). "However, the expression of DKK1, a secreted inhibitor of WNT signaling, significantly changed in both cancer cell lines but exhibited opposite trends in CRC and PDAC cell lines." (PMID 40013338, 2025). "Additionally, the synchronous expression of both DKK1 and CKAP4 seems to result in a worse prognosis in different types of cancer." (PMID 39795613, 2025). "However, recent preclinical and clinical studies have revealed that the interaction of DKK1 and CKAP4 on the cell membrane activates the Akt signaling pathway, wherein various types of cancers predominantly rely on cell proliferation." (PMID 40282454, 2025). "Nonetheless, in cancer cells expressing CKAP4 but not DKK1 the anti-CKAP4 antibody did not exhibit such efficiency." (PMID 41149482, 2025). "We further performed real‐time PCR in four cancer tissues and four noncancerous epithelial tissues, and found that DKK1 was highly expressed in HNSCC (p = 0.0473)." (PMID 38525111, 2024). "Therefore, exploring DKK1’s role in Ov-CCA and its impact on NF-κB and Wnt/β-catenin crosstalk is crucial for identifying potential anti-cancer therapy targets." (PMID 39236081, 2024). "In concordance with its undetectable transcript expression, DKK1 staining was not present in the murine cancer lines." (PMID 38659818, 2024). "Despite the promising results in preclinical mouse models, the outcomes of the clinical trials were less robust, and anti-DKK-1 antibodies have not been FDA-approved for treating cancer patients." (PMID 37174109, 2023). "In addition, decreased cortical bone volume in the DKK-1 group suggested that DKK-1 induced bone resorption, which facilitated the cancer cells to penetrate the cortical bone." (PMID 38067123, 2023). "To date, the effects of dual inhibition of sclerostin and DKK-1 in cancer models have not been investigated." (PMID 37174109, 2023). "It has been reported that DKK-1 induces cancer growth through the activation of the non-canonical WNT/PCP pathway through the activation of JNK proteins." (PMID 38067123, 2023). "Dickkopf1 (DKK1) is a quintessential Wnt antagonist produced by a variety of cell types including platelets, endothelial cells, and is known to modulate pro-inflammatory responses in infectious diseases and cancer." (PMID 37885890, 2023). "Several studies have shown that DKK-1 contributed to cancer progression independent of the canonical WNT signaling." (PMID 38067123, 2023). "Barbolina and colleagues reported that matrix rigidity, but not mechanical strain, represses DKK1 expression and induces Wnt signaling – a mechanism important for cancer invasiveness." (PMID 37532804, 2023). "DKK1 is a secreted factor that has immune inhibitory effects through suppressing the proliferation of CD8+ T cells and NK cells, thus leading to immune evasion of cancer cells." (PMID 35517499, 2022).
cancer (continued). "We collected the conditioned medium from SCP46 cancer cells stimulated by RSPO2 or RANKL with or without DKK1 knockdown and then injected the conditioned medium i.p. into mice every day for 21 days." (PMID 34847079, 2022). "Strikingly, BCSCs were sufficient to convert the accompanying non-metastatic SUM159-luc cells to highly metastatic, while co-injection of DKK1-depleted BCSCs abrogated this effect, indicating a critical role of the BCSC secretome in promoting cancer metastasis." (PMID 35296660, 2022). "Collectively, DKK1 promotes metastatic colonization of cancer cells without an impact on early cancer cell infiltration." (PMID 35296660, 2022). "In addition, the Wnt inhibitors DKK1 and SOST secreted by MSCs, osteocytes or cancer cells were found to induce slow cycling or a dormant state in multiple myeloma, breast, lung and liver cancers." (PMID 36497192, 2022). "Noggin, similar to DKK1, acts as an antagonist to osteoinductive Wnt proteins in osteolytic cancer cells, and as expected, noggin is not expressed in osteoinductive cancer cell lines." (PMID 34685470, 2021). "Taken together, these results demonstrated that differential DKK1 expression had a non-directional effect on the progression and prognosis of certain cancers." (PMID 34899842, 2021). "Although the effects of DKK-1 pharmacological inhibition have not been evaluated in cancer, it has been shown that WAY-262611 inhibits both cell migration and expression of focal adhesion kinase (FAK) in fibroblast-like synoviocytes." (PMID 34884726, 2021). "The use of vitamin D to improve cancer treatment has been evaluated, even when its effect on DKK-1 was not identified, based on epidemiologic studies that correlate the incidence of cancer and sun exposure." (PMID 34451907, 2021). "Treatment of ROR2-overexpressing cells with soluble WNT ligand antagonists such as sFRP1 or DKK1 as well as an inhibitor blocking non-canonical WNT-JNK signaling inhibited ROR2-induced cancer cell invasiveness." (PMID 34911552, 2021). "Although the functional mechanism of DKK1 has not yet been fully elucidated, its role in signaling pathways in cancers and immune cells has become increasingly apparent." (PMID 34093545, 2021). "Besides, induction of Dickkopf-related protein 1 (DKK1), an endogenous inhibitor of LRP5 and LRP6, results in the delay of cancer progression." (PMID 34959397, 2021). "Herein, we also demonstrate that to identify prognostic genes by comparing gene expression between cancer and control samples is not reliable approach (DKK1)." (PMID 32489468, 2020). "In addition, the proto-oncogene c-Myc is also a key oncogenic component of the WNT/β-catenin signaling pathway through transcriptional repression of the secreted Wnt inhibitors DKK1 and SFRP-1 in cancer cells." (PMID 30348169, 2018). "In this regard, various groups have reported that dickkopf-1 (DKK1), a soluble inhibitor of Wnt/β-catenin signaling that supports an immunosuppressive environment and epithelial-mesenchymal transition (EMT), is frequently overexpressed in cancer." (PMID 29662668, 2018). "In addition to the high expression of VEGFR2 after DKK-1 stimulation, it has been known that VEGFR2 can promote angiogenesis and blockage of VEGFR2 can prohibit cancer invasion." (PMID 28938611, 2017). "We found six genes, ADIPOQ, DKK1, IGF1, IGF1R, IGF2, and PLAUR were shared by all the four cancers." (PMID 28676692, 2017). "We measured DKK‐1 autoantibodies in serologic samples from the training and validation cohorts and found that levels of DKK‐1 autoantibody were significantly higher in cancers than in controls." (PMID 26988995, 2016).
cancer (continued). "Finally, DKK1, an antagonist of the Wnt signalling pathway, was demonstrated to complement AFP in HCC diagnosis particularly in AFP-negative cancers." (PMID 27219517, 2016). "Our results show for the first time that a proportion of DKK-1 is located in the nucleus of human enterocytes and malignant epithelial cells in CRC and regulates the expression of a number of genes including several that are relevant for cancer." (PMID 25788273, 2015). "Transient transfection of GATA6, but not mutant GATA6, into cancer cell lines led to decreased DKK1 mRNA expression and secretion of DKK1 protein into culture media." (PMID 21811562, 2011). "We evaluated patients' bone homeostasis; we made peripheral blood mononuclear cell (PBMC) cultures to detect in vitro osteoclastogenesis; we dosed serum expression of molecules involved in cancer induced osteoclatogenesis, such as RANKL, OPG, TNF-alpha, DKK-1 and IL-7." (PMID 18978943, 2008). "In conclusion, as DKK1 is specifically expressed in common cancers, and absent from essential normal tissues, this protein is a potential TA for cancer immunotherapy." (PMID 17245340, 2007). "Taken together, these results suggest that DKK1 contributes to fibroblast activation and cancer cell-fibroblast interaction in high DKK1-expressing tumors, highlightning DKK1 as a potential therapeutic target across various cancer types, not just in gefitinib-resistant NSCLC." (PMID 40025612, 2025). "DKK1 gene dependency analysis using Depmap database also confirmed that neither CRISPR knockout nor RNA interference induced cell death in various cancer cell lines." (PMID 40025612, 2025). "However, neither HCC827-LV con nor HCC827-DKK1 OE produced TGF-β, indicating that the reduction of myofibroblast traits by DKK1 is not due to changes in TGF-β production by cancer cells." (PMID 40025612, 2025). "Thus, the combination of anti-DKK1/CKAP4 and anti-PD-1 treatment may have promising results in anti-cancer treatment." (PMID 41149482, 2025). "In summary, DKK1 exerts its immunomodulatory effects by enhancing Th2 cell responses, impairing T cell function via myeloid-derived suppressor cell (MDSC) regulation, and inhibiting the growth of CD8+ T lymphocytes and NK cells, thereby enhancing inflammation and cancer immune escape." (PMID 38376441, 2024). "Our findings, together with previous reports, demonstrated the regulatory effects of DKK-1 in the cancer–bone microenvironment, supported multiple roles of DKK-1 in noncanonical WNT and other signaling pathways, and indicated that DKK-1 could be a promising therapeutic target for PCa." (PMID 38067123, 2023). "DKK-1 increased cancer growth and stimulated cell migration independent of canonical WNT signaling." (PMID 38067123, 2023). "It will be of particular interest to decipher whether the nuclear appearance of DKK1 is a cancer-specific phenomenon or also detectable in non-malignant cells." (PMID 36539532, 2022). "However, it is unclear why DKK1 expression increases in cancers in which Wnt signaling is not activated aberrantly." (PMID 34117362, 2021). "To summarize, DKK1 had immunoregulatory effects, including promoting Th2 cells response, reducing the functionality of T cells through MDSC modulation and suppressing the proliferation of CD8+ T cells and NK cells, thus contributing to inflammatory response and cancer immune evasion." (PMID 34093545, 2021). "Because we investigated the association between HCC and angiogenesis in this study, we could not provide evidences to explain the reason why DKK-1 acts differently in various cancer types." (PMID 28938611, 2017).